EGF (epidermal growth factor)
Diseases named in the same sentence as EGF in open-access papers (continued):
Sharing a sentence is not in itself a finding about the gene and the disease.
melanoma (continued). "Here, we describe that the transcription factor NRF2, the master regulator of the oxidative and electrophilic stress response, mediates the expression and activation of EGFR in melanoma by elevating the levels of EGFR as well as its ligands EGF and TGFα." (PMID 33916908, 2021). "Decreased concentrations of BDNF, SDF-1α, MCP-1, Eotaxin, and EGF were observed in primary melanoma and metastatic melanoma patients compared to healthy subjects." (PMID 33574842, 2021). "Chimeric and murine anti-EGF antibodies have proven effective in suppressing metastasis in a murine model for human melanoma." (PMID 34360915, 2021). "Suppression of MITF was also associated with increased expression of ligands synergizing with EGFR activation, and autocrine EGF-EGFR circuit was observed in the cultures of resistant melanoma cell lines." (PMID 31936151, 2020). "A high plasticity of resistant melanoma cells was also detected as the rapid regrowth and reprogramming of EGF-dependent EGFRhigh trametinib-resistant cells subjected to drug holiday." (PMID 31936151, 2020). "Epidermal growth factor (EGF) was the single protein differentially regulated in pathways including melanoma, phospholipase D signaling and PI3K-Akt signaling pathways." (PMID 32265830, 2020). "Although we did not observe the intrinsic phosphorylation of EGFR in any cell line, the differences in the response of the melanoma cells with SIRT2-downregulation to EGF was evident." (PMID 31091806, 2019). "We also found that the expression of amphiregulin, a member of the epidermal growth factor (EGF) family, was correlated with IL13Rα2 expression in cultured melanoma cells, xenograft tumour tissues and melanoma clinical samples." (PMID 30718742, 2019). "Melanoma cells often overproduce EGF, which in turn by the autocrine stimulation positively influences their growth and rate of metastasis." (PMID 31649529, 2019). "Our thesis is corroborated by the fact that we have recently shown that administration of EGF and HGF on melanoma cells causes a decrease in the filamentous to monomeric actin ratio, what was correlated with cells’ increased invasive potential." (PMID 29719603, 2018). "An early analysis of the expression of growth factors and their receptors in melanomas showed that EGF was overexpressed as compared to melanocytes while EGFR was expressed in both melanomas and melanocytes." (PMID 27102439, 2016). "Stem cell medium (SCM) was used to propagate patient-derived melanoma cell cultures as we have previously shown that this medium containing growth factors EGF and bFGF better preserves the original tumour characteristics than serum-containing medium." (PMID 27351373, 2016). "In the present study, we have used treatment-naïve patient-derived melanoma populations to unravel how melanoma cells exploit survival signals when microenvironment components, particularly growth stimuli EGF and bFGF are replaced by serum." (PMID 26035829, 2015). "Knockdown of EGF in EGF over-expressing melanoma cells results in reduced lymph node metastasis, which is considered a key initial step of melanoma progression." (PMID 25763355, 2015). "Heterogeneous melanoma populations characterized by long-term growth and a high self-renewal capacity can be obtained in vitro in EGF(+)bFGF(+) medium whilst invasive potential of melanoma cells is increased in serum-containing cultures." (PMID 26035829, 2015). "In the present study, we concentrated exclusively on early pro-survival response of melanoma cells to changes in the microenvironment, namely to the replacement of bFGF and EGF with serum." (PMID 26035829, 2015). "We have shown that MITF level and activity correlates well with the extent of heterogeneity of patient-derived melanoma cultures in EGF(+)bFGF(+) medium." (PMID 26035829, 2015).
melanoma (continued). "We have already shown that different patient-derived melanoma populations grown in vitro in EGF(+)bFGF(+) medium exhibit diverse morphology and molecular characteristics regarding immunophenotype and expression of MITF and MITF-dependent genes." (PMID 26035829, 2015). "In melanoma, the autocrine and paracrine actions of EGF and EGFR contribute to tumor cell proliferation and migration." (PMID 26079945, 2015). "In an earlier study, knockdown of EGF led to markedly reduced migration and in vivo lymph node metastasis in melanoma cells expressing high levels of EGF." (PMID 26079945, 2015). "When melanoma cells from EGF(+)bFGF(+) cultures were transferred to serum-containing medium, flow cytometry analysis showed no signs of apoptosis in DMBC12 and DMBC19 populations 4 h and 25 h after medium exchange when compared to control cells (0 h)." (PMID 26035829, 2015). "A7 melanoma cells transfected with ARHGAP22 were stimulated with EGF (50 nM) for 30 min and lamellae formation was analyzed by F-actin staining." (PMID 24933155, 2014). "The subgraphs in the melanoma mutation network revealed featured pathways such as the Raf/MEK/ERK pathway and receptor signaling pathways (e.g., EGF/EGFR, FGF, PDGFR-beta signaling pathways)." (PMID 24516372, 2014). "Transcriptome analysis of the various cell subsets purified from RETAAD tumors showed that PMN-MDSC express TGF-β1 and HGF, whereas melanoma cells express EGF." (PMID 21980263, 2011). "The only other report of EGF and TGFβ1 effects on ILK expression, showed stimulation of ILK expression in a human melanoma cell line following exposure to EGF and TGFβ1 for 24 and 48 hours." (PMID 16643659, 2006). "Additionally, a preclinical study has shown that anti‐EGF vaccination antibodies enhanced the activity of MAPK/ERK and PI3K/AKT inhibitors and reduced the proliferative effects of NRAS mutation melanoma cell lines." (PMID 41492362, 2026). "Another example of EGF-functionalized AuNPs for photothermal therapy (PTT) consisted of multifunctional hybrid nanocarriers combined with near-infrared (NIR) laser irradiation for the treatment of melanoma." (PMID 39940134, 2025). "Moreover, we also confirmed that colony growth of malignant melanoma cells in anchorage-independent condition was dramatically increased in the stably cGAS overexpressing cells by EGF or bFGF stimulation." (PMID 39424777, 2024). "Importantly, the impacts of KIF22 depletion on the progression of melanoma were partially attenuated after EGF or Colivelin treatment." (PMID 37944197, 2023). "We found that “NF-kappa B” and “EGF” are early fields in the study of NF-κB in melanoma." (PMID 36124033, 2022). "Specifically, we could resolve the coordinated and synchronized assembly (and disassembly) of NRas and BRAF in co-clusters at the PM of live, EGF-activated 108T melanoma cells." (PMID 36304112, 2022). "The value of EGF activity determined from plasma and tissues was major in the case of the melanoma group, with a significant decrease in the case of individuals treated with rhodoxanthin, and the variation of 8-OhdG concentration was similar to that of EGF." (PMID 36421450, 2022). "OPN also is upregulated in several human melanoma cell lines after EGF stimulation." (PMID 34067095, 2021). "G-361 melanoma cell reduction was produced because of a decrease in the extracellular pH, which results in a reduction in the intracellular glucose level with the inhibition of mTOR and EGF survival pathways and leads to autophagy activation." (PMID 32178401, 2020). "STAT5 activation is induced by the EGF/JAK1 axis in melanoma cell lines." (PMID 31569642, 2019). "Interestingly, MC38, PM299L, and Hepa129 derived tumor extracts presented significantly higher EGF levels than B16-OVA melanoma extracts." (PMID 31921216, 2019). "This suggests a role for EGF-EGFR-based autocrine signaling in melanoma cells." (PMID 27102439, 2016).
melanoma (continued). "This screening has shown that concentrations of 15 biomarker proteins (IL-1α, IL-1β, IL-6, IL-8, IL-12p40, IL-13, G-CSF, MCP-1, MIP-1α, MIP-1β, IFN-α, TNF-α, EGF, VEGF, and TNF-RII) were significantly higher in patients with resected high-risk melanoma compared with healthy controls." (PMID 28050120, 2016). "Melanoma populations grown in EGF(+)bFGF(+) medium may also be endowed with a unique composition of pro-survival machinery as shown for highly up-regulated BCL2A1 in heterogeneous melanospheres." (PMID 26035829, 2015). "Altogether, these results demonstrate that patient-derived melanoma populations cultured in EGF(+)bFGF(+) medium may markedly differ in expression of MITF and MITF-dependent genes, but also in regard to the baseline pro-survival machinery." (PMID 26035829, 2015). "As melanoma cells cultured in EGF(+)bFGF(+) medium were well protected from cell death during early adaptation to serum-containing medium, we next verified whether this advantage was associated with changes in the pro-survival machinery." (PMID 26035829, 2015). "We have shown recently that melanoma cells directly derived from surgical specimens and grown in bFGF(+)EGF(+) stem cell medium as anchorage-independent melanospheres more closely resemble the original tumors than do monolayers maintained in the presence of serum." (PMID 26035829, 2015). "Since the original report, majority of studies conducted in different Caucasian populations have not confirmed such an association between the EGF +61A>G polymorphism and the predisposition to melanoma or nevi development." (PMID 19624835, 2009). "What had already been demonstrated in the literature in vitro was that EVOOO extracts reduced non-melanoma skin cancer cell viability and migration, prevented colony and spheroid formation, and inhibited the proliferation of atypical keratinocytes stimulated with the epidermal growth factor." (PMID 40565713, 2025). "While the role for EGFR signalling in anoikis resistance in melanoma cells remains poorly defined, it is hypothesised that the sustained survival signalling provided by autocrine EGF/EGFR activation within clusters of melanoma cells contributes to the survival of disseminated cells." (PMID 37181747, 2023). "Therefore, we depleted LRIG1 in human melanoma cells (A375) by CRISPR/Cas9 technology and found that this caused EGFR and ERBB3 downregulation in A375 LRIG1 knockout cells 6 h following stimulation with EGF." (PMID 33786987, 2021). "Considering the previous controversial reports, findings of current study suggest that sphere culture condition, containing serum-free medium, EGF, bFGF, and B-27 at the low attachment plate, could be more reasonable method to obtain enriched melanoma SCs from CD133+ sorted cells." (PMID 27054115, 2016). "Our previous studies have pointed that melanoma populations that were first cultured in EGF(+)bFGF(+) medium and then transferred to serum-containing medium for at least two weeks could be characterized as having reduced self-renewal capacity and heterogeneity and a high invasive potential." (PMID 26035829, 2015). "An increase in Annexin V-positive cells and apoptotic/necrotic cells was obtained when melanoma population with silenced expression of MCL-1 was exposed to serum-containing medium when compared to the same population concomitantly exposed to fresh EGF(+)bFGF(+) medium." (PMID 26035829, 2015). "Prevalence of EGF genotypes and allele frequencies among melanoma and non-melanoma subjects." (PMID 19624835, 2009). "A study by Girotti and others demonstrated that BRAFi-resistant melanoma cell lines express high levels of phosphorylated EGFR, and secrete increased levels of EGF." (PMID 37181747, 2023). "We suggest that gastrin liberates factors from stromal cells (i.e. members of the EGF and IGF families have already been established as gastrin targets in other systems) which then stimulate melanoma invasion and migration." (PMID 38069171, 2023).
melanoma (continued). "Conversely, EGF led to the nuclear localization and activation of NRF2, thereby demonstrating that NRF2 and EGFR are connected in a positive feedback loop in melanoma." (PMID 33916908, 2021). "GPER activation is connected with transactivation of epidermal growth factor, mitogen-activated kinase, ERK kinase, and 3-phosphatydyloinositole pathways, which are involved in pathogenesis of melanoma." (PMID 34833446, 2021). "Compared to the control group, melanoma patients had higher levels of VEGF-A, PDGF-BB, IL-1RA, PIGF-1, IFN-γ, TNF-α, MIP-1α, and SCF, but lower levels of BDNF, SDF-1α, MCP-1, Eotaxin, EGF, and IL-7." (PMID 33574842, 2021). "In conclusion, our study demonstrated that LRIG1‐TG mice develop melanocytic skin tumors during chemical skin carcinogenesis and a deletion of LRIG1 in human melanoma cells reduces EGFR and ERBB3 expression after EGF stimulation." (PMID 33786987, 2021). "We previously showed that EGF and HGF stimulate invadopodia formation and extracellular matrix degradation, which correlates with higher invasive abilities of melanoma cells." (PMID 31649529, 2019). "Throughout all experiments, cells were treated with 5 nM EGF and 30 ng/ml HGF to mimic conditions present in the melanoma microenvironment." (PMID 31649529, 2019). "EGF has a promising therapeutic value as a targeting ligand for tumours overexpressing EGFR, such as melanoma." (PMID 27788212, 2016). "For example, EGF signaling confers resistance to BRAF inhibition and induces melanoma invasion through Src pathways." (PMID 25763355, 2015). "Based on previous studies showing upregulation of EGF and EGF receptor (EGFR) in malignant melanoma, the correlation between Swiprosin-1 expression and EGFR signaling was examined." (PMID 26079945, 2015). "For this purpose, melanoma cell lines were exposed to various cytokines (EPO, EGF, TGF-ß1, Heregulin-α, IGF-1, HGF, SCF, NGF) and then were subjected to qPCR analysis and flow cytometry." (PMID 24489649, 2014). "Published accounts of chemotactic invasion most often describe growth factors as the attractants—for example EGF for solid tumours, and EGF, hepatocyte growth factor (HGF), and stem cell factor (SCF)/KitL for melanoma." (PMID 25313567, 2014). "EGF and TGF-α have closely related tertiary structures and they compete for binding to the EGF-receptor which has been shown to be overexpressed in melanoma cells." (PMID 24457057, 2014). "In the melanoma literature, most chemotaxis is attributed to growth factors such as platelet-derived growth factor (PDGF) and EGF and the CXCR4 ligand SDF-1, though a wide variety of potential attractants have been discussed." (PMID 25313567, 2014). "Our data demonstrate that MMP13 links growth-stimulatory signals such as EGF and FCS to cell cycle progression in melanocytes and melanoma cells and to dedifferentiation in melanocytes." (PMID 20667128, 2010). "Taken together, these data suggest that all mutants were correctly expressed and normally responded to EGF stimulation, and C797S mutation did not enhance the autophosphorylation of T790M/L858R in EGFR-negative melanoma cells." (PMID 40649937, 2025). "VHL-Mb24 reduced ERK phosphorylation levels following EGF stimulation of NRAS expressing RASless HEK cells but did not affect ERK phosphorylation levels in NRASQ61L-mutant WM-1366 melanoma cells." (PMID 39379700, 2024). "Furthermore, Cu-B inhibits MEK 1/2 as well as the constitutive and EGF-induced ERK 1/2 activation, indicating a definitive involvement of MAPK signal transducers in regulating Cu-B-mediated anti-melanoma activity." (PMID 35756619, 2022). "Because the addition of T cells to melanoma cultures inhibits expression of CD206, we hypothesize that EGF expression may also be limited, resulting in decreased CCL2 levels and inhibited myeloid chemotaxis to sites." (PMID 35265066, 2022).
melanoma (continued). "TAMs secrete proteases, and cytokines, such as epidermal growth factor (EGF) or VEGF, which may further promote the epithelial-mesenchymal transition of melanoma cells, thus favoring cancer cell invasion, metastasis and neoangiogenesis." (PMID 35406483, 2022). "Moreover, Cu-B inhibited both the constitutive as well as EGF-induced ERKphosphorylation, indicating the role of MAPK signaling in regulating the chemotherapeutic potency of Cu-B against melanoma." (PMID 35756619, 2022). "The in vitro experiments indicated that the EGF gave the melanoma cell targeting ability without influence on the tissue penetration function of SPACE." (PMID 34064297, 2021). "In this study, melanoma patients showed higher levels of VEGF-A, PDGF-BB, IL-1RA, PIGF-1, IFN-γ, TNF-α, MIP-1α, and SCF, but decreased levels of BDNF, SDF-1α, MCP-1, Eotaxin, EGF, and IL-7 than those in healthy patients." (PMID 33574842, 2021). "Moreover, as deprivation of exogenous EGF was enough to trigger inhibition of EGFR signaling, production of EGFR-activating ligands in resistant melanoma cells was insufficient." (PMID 31936151, 2020). "Our hypothesis for this study suggested that CAP and SN co-effectively blocked the classical PI3K/mTOR and EGF/MEK survival pathways, which will eventually lead to the activation of autophagy in G-361 human melanoma." (PMID 32178401, 2020). "AREG is a member of the epidermal growth factor (EGF) family and signals through epidermal growth factor receptor (EGFR), notably found on muscle cells and tumor cells including colon, breast, prostate, pancreatic, bladder, ovarian, and melanoma." (PMID 31681327, 2019). "Additionally, PMN-MDSCs can promote EMT in melanoma cells through activation of the TGF-β, epidermal growth factor (EGF) or hepatocyte growth factor (HGF) signaling pathways, leading to enhanced metastasis." (PMID 30200242, 2018). "In addition to TGFβ and WNT5A signaling, EGF, FGF, MET, and IGF signaling have established roles in conferring migratory and invasive functions in melanoma." (PMID 25763355, 2015). "The melanoma cell line A375 reportedly expresses human EGFR and responds to addition of EGF." (PMID 20663135, 2010). "EGF-dependence was limited to the trametinib-resistant cell line with elevated level of EGFR expression/phosphorylation, and it was conditional as excluding trametinib from the culture medium lacking EGF resulted in the rapid regrowth and reprogramming of melanoma cells." (PMID 31936151, 2020). "In addition, both EGF and PDGF can increase the activity of ERK signaling in melanoma." (PMID 24586666, 2014). "Surprisingly, EAI045 completely blocked EGF-mediated phosphorylation of T790M/L848R and T790M/C797S/L858R, but just slightly decreased pAkt levels, suggesting that these two mutants may enhance pAkt independently of the phosphorylation of EGFR at tyrosine 1173, at least in these melanoma cells." (PMID 40649937, 2025). "In addition, epidermal growth factor (EGF) increases the levels of extracellular signal-regulated kinase 1/2 (ERK-1/2) with hair follicle-derived mesenchymal stem cell proliferation, and activation of p38 by hepatocyte growth factor (HGF) induces the proliferation of melanoma cells." (PMID 39338277, 2024). "Importantly, replacement of EGF/bFGF with serum (FBS) induces growth as monolayers, significantly reduces stem-like features including self-renewal capacity, enforces proliferation and invasive potential of melanoma cells, all preceded by substantial alterations in the gene expression profile." (PMID 26035829, 2015). "In particular, the obtained results revealed the potent inhibiting effect of these compounds on the EGF-, TPA-, X-ray-, and UVB-induced neoplastic cell transformation of non-cancerous cells and the colony formation of human melanoma cells." (PMID 35323516, 2022).